IL2 (interleukin 2)
Diseases named in the same sentence as IL2 in open-access papers (continued):
Sharing a sentence is not in itself a finding about the gene and the disease.
infection (continued). "We observed that R5/X4 HIV-GKO total infection (productive and latent), as well as cell viability, were higher in CD4+ T cells stimulated with IL-15 compared to IL-2 stimulated." (PMID 35499323, 2022). "The variables that best predicted the infection status were the TNF-alpha and IL-2 value from the second sampling, leading to AUC values of 0.742 and 0.745, respectively." (PMID 36560410, 2022). "Across in ovo treatment, the expressions of IL-2, IL-6, IL-10, TGF-β4, TLR-4, 1α-hydroxylase, and VDR were significantly higher at 2 wk post-infection (28 doa) in comparison to their expression levels before coccidiosis infection (14 doa)." (PMID 36230268, 2022). "Memory cell numbers and frequencies quantified 6, 9, and 12 days post-Lm-N4 challenge infection were significantly lower (factor of 2–4) when OT-I cells had been primed with weak TCR and IL-2 signals." (PMID 35474218, 2022). "Since HPgV-1 slows cellular proliferation induced by IL-2 or TCR-stimulation, this may reflect a virus-driven interference with Src kinase-mediated cellular proliferation, resulting in gradual loss of infected cells that produce such low levels of virus that infection of new cells is gradually lost." (PMID 35707535, 2022). "Frequency IFN-γ and IL2 responses to CD4+CD8 pools and S, N, and M pools in matched asymptomatic and symptomatic post-infection participants." (PMID 35390102, 2022). "Echinococcus granulosus s.s. has been shown to regulate host immunity by biasing a Th1/Th2 response towards a chronic Th2 response, as the infection was found to induce a marked increase in the transcriptional levels of IFN-γ, IL-2, IL-4, IL-5, and IL-10." (PMID 36289514, 2022). "Previous studies have shown significantly higher concentrations of IFNα, IL-2, IL-6, IL-12p70, CXCL10, and GM-CSF in patients with a clinical diagnosis of prolonged post-infection fatigue (>6 months) reporting a history of symptomatic WNV infection." (PMID 35458486, 2022). "CD4+ T cells are crucial in the whole-body resistance to HAV infection, and they produce a large number of cytokines in the early stages of infection, including IFN-γ, TNF-α, IL-2, and IL-21." (PMID 36248427, 2022). "Some studies have suggested that IL-1β, TNF-α, IL-2, IFN-γ, and IL-6 were markedly upregulated in critical patients after infection with SARS-CoV-2 and thus can be used as biomarkers to determine the severity of disease in patients." (PMID 36069561, 2022). "During the infection, Th1 cytokines such as IFN-γ, IL-2 and TNF are essential for supporting the expansion and maturation of CD8+ T lymphocytes and B cells." (PMID 35887351, 2022). "5-day-old Pekin ducklings were infected with the R38K, T151A, and R304M mutant viruses and the rY and rPS control viruses, and the levels of IL-2, IL-17, IFN-γ, TNF-β, CD4, and CD8 mRNAs in brain and thymus were measured at 7 days after infection." (PMID 36016955, 2022). "Incision infection after calcaneal fracture affects the clinical treatment effect, and serum IL-2, IL-6, and CRP levels increase in patients with postoperative incision infection after bone fracture." (PMID 36091601, 2022). "TMUV induces significant up-regulation of IL-2 and IFN-γ at 7 days post infection (pi), and significant increases in numbers of CD4+ and CD8+ T cells at 5 days pi." (PMID 36016955, 2022). "In the case of SARS-CoV-2, an increase in the concentration of inflammatory cytokines such as IL-1β, IL-2, IL-6, IL-7 and TNF-α comes to the fore, along with the rise in IL-4 and IL-10 concentrations in a later stage of infection." (PMID 36294388, 2022). "We examine the levels of TNF-α, IL-12, IFN-γ, IL-2, TGF-β, IL-10, IL-17, and IL-6 in lung lysates obtained from M. tb-infected mice at different timepoints post-infection." (PMID 35453358, 2022). "Tc1 cells are capable of producing IL-2, IFN-γ, and TNF-α, cytokines recognized for playing critical roles during infection." (PMID 35214766, 2022).
infection (continued). "The levels of IL-2, IL-6, and TNF-α increased more than 80-fold upon infection with the ∆katG mutant." (PMID 35438052, 2022). "Th1 cytokines (IL-1β, IL-2, IL-12p70, IFN-γ and TNF-α), Th2 cytokine (IL-4), as well as Th17 cytokine (IL-17A) showed decreasing trend by infection intensity." (PMID 36083861, 2022). "CD8+ T cytotoxic lymphocytes produced type I cytokines, such as IL-2 and IFN-γ, to serve as the first-line defense mechanism and obtained acquired immunity during post-infection or T-cell clone expansion." (PMID 34200327, 2021). "Although this was the case, the noticeable decreases in IL-1β, IL-2, IL-4, IL-12, IL-13, RANTES, TNF-α, and GRO-α observed in patients with lethal SARS-CoV-2 infection suggest that lethal infection results in an exhausted immune response." (PMID 33472985, 2021). "Particularly, infection upregulated the cytokines IFN-γ, IL-12b, and IL-2 (126-, 44-, and 18-fold change, respectively) and the T-cell chemoattractants CCL3 and CCL5 (23- and 16-fold change, respectively)." (PMID 34381739, 2021). "The PLS showed that the levels of GMCSF, Fractalkine, IFNg, ITAC, IL-1ß, IL-2, IL-5, IL-7, IL-8, IL-10, IL-12, IL-17α, IL-21, IL-23, MIP-1ß, and TNFα had higher impact on the separation between the uninfected and the pre-infection cohort." (PMID 33731158, 2021). "Minimal differences were detected for monocyte chemoattractant protein 1 (MCP-1), RANTES, IL-2, IFN-γ, IL-10, IL-12(p40), and IL-12(p70), except during primary infection with D39Δ1098 and D39ΔproB." (PMID 33875471, 2021). "The IL-2/INFγ ratio was above the cut-off value of 0.09 for 27 ICU patients, which constitutes 90% of all the patients with a critical course of the infection." (PMID 34071149, 2021). "The amounts of CD8+ and CD4+ T cells producing IL-2 in the populations of mice splenocytes were additionally analyzed by ICS on days 14 and 29 after VACV LIVP infection." (PMID 34452494, 2021). "E challenge infection; the number of IFN-γ, IL-2, IL-4, and in particular IL-17 producing splenocytes from mice that had been vaccinated i.n. with c-di-AMP-adjuvanted 5cVAC increased drastically due to re-stimulation with 5cVAC." (PMID 34204170, 2021). "The levels of IL-2, G-CSF, IFN-γ, and RANTES were significantly higher in the Nlrp3−/− mice than the wild-type mice on day 7 post-infection." (PMID 34690967, 2021). "Among serum molecules identified in non-neurological and neurological diseases in the acute phase of the infection, 12 (IL-1β, IL-6, TNF, IL-2, IL-7, IL-17A, IL-15, IFN-α, IL-5, IL-13, IL10, and GM-CSF) were shared by both networks." (PMID 33776990, 2021). "Our data showed that upon anti-IL-2 mAb administration, mice had fewer CD4+CD25+Foxp3+ T cells at day 21 post-infection." (PMID 34869064, 2021). "PD-1 blocking significantly increased IL-2 (p < 0.05) and IFN-γ (p < 0.05) production in the serum from CP BVDV-infected mice at day 7 of post-infection." (PMID 34552590, 2021). "After infection diagnosis, PGE2 showed only positive correlations with pro-inflammatory cytokines such as TNFα, IL-2, IL-15." (PMID 33617528, 2021). "Interleukin-2 (IL-2) and tumor necrosis factor (TNF) were lost early, whereas interferon-γ (IFN-γ) production persisted longer after infection." (PMID 34354714, 2021). "The percentage of IFN-γ-secreting CD8+ T cells increased significantly after infection (P < 0.05), while it decreased significantly in infected TLR7 KO mice, as well as IL-2 and IL-6 (P7 < 0.05)." (PMID 34692568, 2021). "The higher proportion of SARS-CoV-2 naive women with IL2 production after SARS-CoV-2 antigenic stimulation suggests that memory responses may be more sensitive than effector responses for the detection of SARS-CoV-2 cross-reactive responses generated by past infection with CCoV." (PMID 35903460, 2021). "Significantly higher levels of IL-2, IFN-γ, and RANTES were observed in Nlrp3−/− mice on day 7 post-infection." (PMID 34690967, 2021).
infection (continued). "The results showed that after infection with YJ016, the plasma levels of IL-2 and IL-23 in the Pair group were higher than those in the EtOH group; IL-13 and IFN-γ were lower in the EtOH group than in the Pair group." (PMID 34489943, 2021). "Despite some variation between individual mice, BALF samples from LVS- and fpt mutant-infected mice showed significantly elevated levels of IFN-γ, TNF-α, IL-1β, IL-12p70, IL-10, IL-2, and KC/GRO compared to mock infection." (PMID 34202420, 2021). "Pro-inflammatory cytokines IL-2, TNF-α, IL-17α, IFN-γ, IL-1β, and MIP-3α are significantly elevated in infection-naïve CF mice (p < 0.050)." (PMID 34475490, 2021). "Successful resolution of the infection requires the host to mount an adequate Th1-type immune response characterised by the production of IFN-γ, TNF and IL-2 by CD4+ and CD8+ T cells." (PMID 33524030, 2021). "Polyfunctionality of these cells in regard to major Th1 cytokine production (MIP-1β, IFN-γ, IL-2) and expression of activation/proliferation markers, i.e., CD69, CD38, CD25, and Ki67, suggest a potential central role in the control of infection." (PMID 34283810, 2021). "Neutralization of IL-2 increased the numbers of recently activated CD4+CD69+ T cells and memory CD4 and CD8 T cells after three weeks of infection and the numbers of splenic T cells producing IFN-γ, TNF-α and IL-10." (PMID 34869064, 2021). "It was found that naive T cells differentiate into effector T cells and further secrete cytokines such as IL-2 and IFN-γto facilitate rapid clearance of the virus at the early stage of the infection." (PMID 34526112, 2021). "In contrast, mRNA levels and cytokine concentrations of IL-2 and IFN-γ decreased after infection, but increased after treatment." (PMID 32635653, 2020). "IL-2 induces CD4+ and CD8+ T cell proliferation and differentiation and stimulates the growth of memory T cells during primary infection." (PMID 33133057, 2020). "Spleen cells recovered on day 30 post-infection from L. donovani-infected mice were enriched in Leishmania-specific clones by the ex vivo stimulation with SLA and IL-2 for 3 days." (PMID 32214337, 2020). "Cultures were grown for ∼2 mo in the presence of IL-2 with periodic CD3/CD28 reactivation, while monitoring for activation markers and frequency of infection." (PMID 33318172, 2020). "T helper (Th1) cells mainly produce IL-2 and IFN-γ and are crucial to defense against intracellular pathogens infection." (PMID 33134305, 2020). "The lung homogenates of WT and AhR−/− mice were collected after 96 h, 2 and 10 weeks of infection and used to evaluate the presence of cytokines (IL-12, TNF-α, IL-1β, IL-6, IL-23, IL-2, IFN-γ, IL-4, IL-17, IL-22, TGF-β, IL-10, IL-27, and IL-35)." (PMID 32647342, 2020). "For example, one study showed that plasma levels of IL-2, IL-6, IL-8, IL-10, and TNF-α, were found to be higher in patients with severe infection than those with mild to moderate infection." (PMID 32984253, 2020). "Second, there was a significant increasing trend in the Th1/ Th2 cytokines IL-2, TNF-a, IL-4, and IL-10 on 5–7 dpi during the middle stage of infection." (PMID 33180882, 2020). "Extracellular ATP levels were raised 24 h after infection (OAd.TNFa-IL2 vs. mock p = 0.002) and extracellular HMGB1 levels were raised after 48 h (OAd.TNFa-IL2 vs. mock p = 0.0114)." (PMID 32225009, 2020). "The Th1 (IL-2 and IFN-γ) response was initially found to be low during infection with A. cantonensis but increased after Alb-Sch B co-treatment." (PMID 32635653, 2020). "The assays used in the two studies differed; the Kumari study used a single-cycle infection assay of PHA and IL-2 activated PBMCs." (PMID 32267841, 2020). "To further ascertain the molecular response during the infection of C. sinensis, we measured the CD4+T cell subsets-related cytokines, including IL-10, IL-17, IL-4, IL-2, and TNF-α by ELISA methods." (PMID 33489026, 2020).
infection (continued). "Ag-expCD4+ T cell effector function continued to deteriorate between days 9 and 15 of infection, with cells on day 15 of infection, expressing low levels of Ki67, ICOS, and CD25 and producing very low levels of TNF, IFN-γ, IL-2, and IL-10." (PMID 32817333, 2020). "Among influenza A/H3N2-infected patients, stimulation with H1N1 elicited a significant increase in IL2+, TNFα+ and polyfunctional CD4+ T-cells, as seen with stimulation with H3N2 suggesting that natural infection does result in heterosubtypic immunity." (PMID 32572168, 2020). "The levels of IL-2, IL-17 and CCL5 at 24 h after infection were regulated in a sex-dependent manner." (PMID 32373108, 2020). "Interleukins (IL), namely IL-2, IL-4, IL-8, and IL-10, and interferons (IFN), IFN-γ and IFN-α, were identified as the main mediators in mice and cotton rats following infection with hMPV." (PMID 31271048, 2019). "Similar control of IL-2 production from CD4 and CD8 T cells by CD70-dependent signals has been found in other infection models." (PMID 31412088, 2019). "In contrast, both routes of infection induced populations of CD4+ T cells producing IFN-γ, IL-2, and TNF." (PMID 31356170, 2019). "IL-2 induces CD4+ and CD8+ T cells proliferation and differentiation, and promotes the development of memory T cells during primary infection." (PMID 31552037, 2019). "In order to explain the reduced SF162 (R5) infection in Th2 cell cultures induced by SEA exposed DCs we characterized the cytokine/chemokine (IFN-γ, IL-4, IL-2, TNF-α, MIP-1β) expression profiles of the different Th cell populations." (PMID 31487324, 2019). "The results indicated that the mRNA expression of IL-2, IL-6, and TNF-α induced by Salmonella CVCC541 infection was significantly inhibited after the JH-3 treatment (p < 0.05)." (PMID 30736473, 2019). "In the late stage of infection, CD8+ T cell-depleted mice had decreased production of IFN-γ and increased production of IL-2." (PMID 31608052, 2019). "Expression of IL-2, important for inducing the Th1 response, was decreased significantly, the levels of TGF-β and IL-17A increased significantly at 30 h after infection." (PMID 31855175, 2019). "The transmembrane domain conjugated IL-2 was ineffective, probably due to low amounts of IL-2 displayed on the cell membrane post vvDD-IL-2-FPTM infection." (PMID 30410056, 2018). "After infection, significantly up-regulated mRNA expressions of immune-related genes were detected in trout skin as early as 12 h (for IL22) or 24 h (IL2, IgT, IgM, and IgD) and reach their peak levels at 7 d, then recovered to control levels by 28 d." (PMID 30619329, 2018). "In this work, we report that both infection with P. berghei ANKA and gonadectomy triggered a sexually dimorphic cerebral mRNA expression pattern of the cytokines IL-1β, TNF-α, IFN-γ, and IL-2." (PMID 30515051, 2018). "Ablation of Il2 in memory CD8 T cell immediately prior to rechallenge did not result in compromised secondary expansion, but ablation prior to primary infection resulted in defective recall responses." (PMID 30619342, 2018). "Second, the characterization of this response revealed a high degree of polyfunctionality including IFN-γ+TNF-α+IL-2+ triple positive CD8+ T-cells, which often correlates with better protection against infection." (PMID 30364187, 2018). "Our findings demonstrate that both infection with P. berghei ANKA and gonadectomy trigger a cerebral sex dimorphic mRNA expression pattern of the cytokines IL-1β, TNF-α, IFN-γ, and IL-2." (PMID 30515051, 2018). "During later periods of infections, CD4+ T cells produce increased amounts of IL-2, which is predominantly consumed by Tregs due to their expression of the high-affinity IL-2 receptor complex." (PMID 30210499, 2018). "At day 6 post-infection, C57BL/6J mice also exhibited higher levels of IL1A, IL1B, CCL2, CCL3, IL2, IL10, and IL6." (PMID 30713529, 2018).
infection (continued). "Exhausted virus-specific T cells also become less responsive to the critical γc survival cytokines IL-2, IL-7, and IL-15 (10, –, 12), although exogenous IL-2 and IL-7 can be used therapeutically to promote virus control in an established LCMV Cl13 infection." (PMID 29593047, 2018). "To investigate lymphocyte activity after infection, we quantitatively determined the presence of IL-2, IFN-γ, TNF-α, IL-4, IL-5, IL-17A, IL-12p70, and IL-22 in mouse sera at day 3, 5, 7, and 9 post-infection; the sera of healthy mice were used as controls." (PMID 30564216, 2018). "Some interactions between peripheral infection and parity were noted for TNF (p = 0.054), IL-12 (p = 0.061), IL-2 (p = 0.003), IFN-γ (p = 0.025), IL-8 (p = 0.151), and IL-5 (p = 0.031)." (PMID 29743113, 2018). "Further, serum levels of interleukin (IL)-2, interferon γ, tumor necrosis factor (TNF)-α, IL-12p70, IL-22, IL-17A, and IL-5 increased significantly after infection." (PMID 30564216, 2018). "Expression levels of the Th1 cytokine IFN-ɣ and the inflammatory cytokine IL-2, an inducer of IFN-ɣ synthesis, decreased in white blood cells post (first) infection." (PMID 29973271, 2018). "The levels of IL-2 and TNF-α were significantly increased while the level of IL-6 was obviously decreased in the infection group compared with the normal control group." (PMID 30305831, 2018). "This suggests a migration of this subset of T cells to the site of infection and a predominantly local relevance of IFN-ɣ and IL-2." (PMID 29973271, 2018). "Nonetheless, in white blood cells, IL-4, IL-6 and IL-10 mRNA-levels significantly increased after infection, whereas IFN-ɣ, IL-2 and TGF-β expression tended to decrease." (PMID 29973271, 2018). "The resulting data indicate that older children respond with diminished levels of the pro-inflammatory cytokines TNF, IL2 and IL6, as well as Th1-biased chemokines when compared to younger children at the same stage of infection." (PMID 29284469, 2017). "The mathematical model has been developed, calibrated and numerically implemented to study various scenarios in the regulation of T cell immune responses to infection, in particular the change in the diffusion coefficient of type I IFN as compared to IL-2." (PMID 28681703, 2017). "Similar to norovirus challenge infections, the natural infection reported here transiently increased serum IFN-γ, IL-2, IL-6 and TNF-α concentrations." (PMID 28815218, 2017). "Patients with infections in the very acute stage (≤ 4 days ill) tended to have the highest IFN-γ, IL-12p70, and IL-2 levels." (PMID 28628633, 2017). "In vivo, we found that that the expression levels of IL-2, IL-4, IL-6 and TNF-a in the lungs of H9N2 infected mice peaked on 2 days post-infection and then declined on days 4 and 6 post-infection." (PMID 28114957, 2017). "This acute phase protein is produced by the hepatocytes in response to IL2, IL1 or TNFα generated during acute infection or tissue damage." (PMID 28401944, 2017). "Eventually, T-cells are primed and activated, which subsequently secrete perforin, granzyme, and cytokines, including interleukin 2 (IL-2) and interferon γ (IFN-γ), to defend infection by inducing the apoptosis of target cells." (PMID 29312360, 2017). "Whereas in mice that experienced lifelong infection with the highest MCMV dose, the IL-2 concentration increased, suggesting a lower rate of IL-2 consumption by the T cells." (PMID 29367854, 2017). "This appears to be the case, as IL-2+MC, more than IL-2+CD90.2 or IL-2+CD4+ T cells, were expanded in vivo, early in infection, particularly in Cftr−/−mice." (PMID 28090087, 2017). "In the present study, both contents and mRNA expression levels of IL-2, IL-8, IL-10, and IFN-γ were influenced by SNE infection and controlled by BS15." (PMID 29209325, 2017). "Host cytokines IL-2, IFN-γ, and TNFα are elevated during infection and have been suggested as markers of active infection, although not specific for TB." (PMID 29237757, 2017).